ENSG00000201863
Synonyms: LOC124900183
Gene: Small nucleolar RNA gene on chromosome 4 (40,082,983 to 40,083,106, forward strand). Ensembl gene ENSG00000201863.
Gene Ontology:
Biological process: RNA processing
Cellular component: nucleolus
Homologues: Paralogues in human: SNORA51 (80% identical).